SAMHD1 (SAM and HD domain containing deoxynucleoside triphosphate triphosphohydrolase 1)
Diseases named in the same sentence as SAMHD1 in open-access papers (continued):
Sharing a sentence is not in itself a finding about the gene and the disease.
cancer (continued). "Our results provide strong evidence of the clinical importance of SAMHD1, becoming an interesting target for the development of personalized cancer treatments." (PMID 35158911, 2022). "Nevertheless, to understand the impact of SAMHD1 downregulation in this cancer type, the CTCL-derived cell line HuT 78 (normally expressing low SAMHD1 levels) was stably transduced with full-length SAMHD1." (PMID 34480199, 2022). "The contribution of SAMHD1 in cancer onset and progression is controversial, with strong evidence demonstrating both its role as a tumor suppressor and as an oncogene." (PMID 35158911, 2022). "In the SAMHD1 high-expression groups, genes were enriched in cancers, cytosolic DNA sensing, chemokine signaling, cytokine-cytokine receptor interaction, apoptosis and antigen processing and presentation pathway." (PMID 36578072, 2022). "Ultimately, SAMHD1 is required to balance cellular dNTP concentrations and/or regulate DNA repair/replication and, therefore, avoid mutagenic conditions favorable for cancer development and progression." (PMID 34480199, 2022). "The functional consequences of SAMHD1 in cancer development and treatment still require further researches." (PMID 36578072, 2022). "Although understanding the consequences of Vpx-mediated SAMHD1 degradation in cancer cells is essential for developing a potential therapeutic strategy, it is also critical to verify the effects of SAMHD1 loss on normal brain tissues." (PMID 36139652, 2022). "SAMHD1, an adenosine triphosphate hydrolase, plays an important role in cancer development, antiviral immune responses, and DNA damage repair and chemoresistance." (PMID 35803902, 2022). "Conversely, SAMHD1 expression can interfere with the anti-cancer efficacy of the triphosphorylated forms of some anti-cancer nucleoside analogues due to the enzyme’s ability to hydrolyze these compounds." (PMID 35893688, 2022). "Overall, our results, and that of others, point toward a tumor type-dependent function of SAMHD1 in cancer onset and/or progression, reflecting once more the great heterogeneity of cancer biology, which deeply challenges the drive for personalized treatment." (PMID 35158911, 2022). "Additional associations were observed between SAMHD1 and SLC642 and any 2+ primary cancers (pLOF + missense, p = 2.40 × 10−7 and p = 5.44 × 10−7, respectively)." (PMID 36199081, 2022). "At present, the role of SAMHD1 in a variety of cancer types has been studied and will be highlighted in this review." (PMID 34480199, 2022). "Together with resistance to apoptosis, SAMHD1 is involved in several cellular processes which are important hallmarks of cancer when dysregulated, as defined and summarized by Hanahan and Weinberg (2011)." (PMID 34480199, 2022). "Based on both the clinical importance of SAMHD1 and the detailed knowledge of its functions and regulation mechanisms, SAMHD1 has become an attractive target for cancer treatment." (PMID 35158911, 2022). "Our findings provide insight into the molecular and mechanical understanding of the autoimmunity and cancer comorbidity, and suggest that SAMHD1 and R-loops are potential and reliable biomarkers in anti-cancer therapeutics." (PMID 33857133, 2021). "SAMHD1 mutations areassociated with the autoimmune disease Aicardi-Goutières syndrome(AGS) and certain cancers." (PMID 33988981, 2021). "Recently, a series of mutations in the multifunctional dNTP triphosphohydrolase (dNTPase), sterile alpha motif and histidine–aspartate domain–containing protein 1 (SAMHD1), have been reported in various cancers." (PMID 34492268, 2021). "The silencing of the SAMHD1 gene leads to increased apoptosis, decreased proliferation, and cytarabine resistance of the cancer cells." (PMID 34976810, 2021). "SAMHD1 is an AGS-associated gene, that is reported to be frequently mutated in multiple types of cancer." (PMID 33857133, 2021).
cancer (continued). "Our study identifies an unexpected function of SAMHD1 in resolving R-loops that accumulate following TRCs, thereby contributing to the maintenance of genome stability and preventing cancer." (PMID 33857133, 2021). "We analyzed The Cancer Genome Atlas (TCGA) database to evaluate the SAMHD1 expression levels in various cancer types." (PMID 33857133, 2021). "Based on its dNTPase activity, SAMHD1 was also reported to detoxify DNA base analogs, currently used in cancer treatment, thus, serving as biomarker predicting low response to these drugs." (PMID 33591315, 2021). "Accumulating evidence indicates that SAMHD1 plays a role in preserving genome integrity and preventing cancer." (PMID 33857133, 2021). "To test the dNTPase activity of SAMHD1 cancer mutants, we purified the catalytic core HD domain (residues 113–626) of some SAMHD1 mutants including R366C/H." (PMID 34492268, 2021). "SAMHD1, a mammalian dNTP hydrolase (dNTPase), increased apoptosis levels and decreased the level of proliferation of cancer cells by regulating the G1/G0 phase." (PMID 33407832, 2021). "RNA sequencing by Expectation Maximization (RSEM) analysis of SAMHD1 expression levels in different cancer types revealed that SAMHD1 expression was downregulated in tumor tissues (red dots) compared to that in normal control tissues (green dots)." (PMID 33857133, 2021). "Next, we tested the antiviral activity of a panel of antimetabolites currently used in cancer treatments in wild type or SAMHD1 depleted macrophages." (PMID 32197329, 2020). "The evaluation of SAMHD1 expression in cancer tissues allowed for the identification of cancer types that would benefit from the pharmacological modulation of SAMHD1 function." (PMID 32197329, 2020). "With this, many consider SAMHD1 as a clinical biomarker of ara-C sensitivity in cancers and have suggested the provision of Vpx along with ara-C during treatment to improve efficacy." (PMID 32244340, 2020). "This precise molecular mechanism for SAMHD1 catalysis, reveals how SAMHD1 down-regulates cellular dNTP and modulates the efficacy of nucleoside-based anti-cancer and anti-viral therapies." (PMID 32576829, 2020). "To further explore the potential value of modulating SAMHD1 function in cancer patients, we evaluated SAMHD1 expression in different tumor tissues by immunohistochemistry (IHC) in paraffin-embedded tissues." (PMID 32197329, 2020). "Here, we reviewed a series of studies that have begun illuminating the highly diverse roles of SAMHD1 in virology, immunology, and cancer biology." (PMID 32244340, 2020). "Despite its downregulation in cancer cells, SAMHD1 expression persists at low levels and interferes with anti-cancer nucleoside analogs, such as ara-C." (PMID 32244340, 2020). "Vpx treatment efficiently depleted SAMHD1 protein and, in line with our data in cancer cell lines, completely abolished the RNRi‐mediated sensitisation to ara‐C toxicity." (PMID 31950591, 2020). "Acetylation at K405 has the opposite effect, stimulating SAMHD1 dNTPase activity, and promoting the transition from G1 into S phase in cancer cells." (PMID 30127789, 2018). "In cancer, SAMHD1 is thought to play a role in controlling cell cycle of tumor cells, where its activity as a triphosphohydrolase can restrain uncontrolled cellular proliferation by blunting cellular DNA synthesis." (PMID 29764952, 2018). "SAMHD1 has recently been proposed as a potential tumor suppressor, and in fact, many FDA-approved anti-cancer TKIs have potent effects on SAMHD1 activation in vitro and in vivo." (PMID 29764952, 2018). "SAMHD1-downregulation caused HeLa cells to grow slower than the control cells, and caused a decrease in MCF7 colony formation, indicating that SAMHD1 expression is important for cancer cell growth." (PMID 28978134, 2017). "Here, we demonstrate that the dNTPase activity of SAMHD1 is regulated by acetylation, which promotes cell cycle progression in cancer cells." (PMID 28978134, 2017).
cancer (continued). "Collectively, these results demonstrate that SAMHD1 acetylation contributes to G1/S transition in cancer cell lines." (PMID 28978134, 2017). "Collectively, these findings suggest that SAMHD1 acetylation enhances its dNTPase activity and promotes cancer cell proliferation." (PMID 28978134, 2017). "Further studies to understand the physiological significance of SAMHD1 in cancer can aid in this process." (PMID 26416562, 2015). "Although numerous studies have investigated the dNTPase function of SAMHD1 in viral restriction and immune responses, its significance in cancer development and progression has lately been an emerging interest." (PMID 26416562, 2015). "This review summarizes the latest advances in understanding the importance of dNTP metabolism in cancer development and the novel function of SAMHD1 in regulating this process." (PMID 26416562, 2015). "With an understanding of SAMHD1 dNTPase function and dNTP regulation in cancer, we discuss the physiological consequences of alterations in SAMHD1 expression." (PMID 26416562, 2015). "We also discuss the potential role of SAMHD1 as a tumor suppressor and future studies required to better understand its function for cancer therapeutic development." (PMID 26416562, 2015). "Based on these recent findings, SAMHD1 is proposed to have anti-proliferative and tumor suppressive functions in several cancers." (PMID 26416562, 2015). "In CLL patient cells, SAMHD1 expression is often reduced as it is the case in several cancer cell lines." (PMID 26606981, 2015). "Collectively, these findings suggest that targeting tumor-specific SAMHD1 represents a novel and promising therapeutic strategy for cancers characterized by elevated SAMHD1 expression, offering potential for improved treatment outcomes in cancer patients with high SAMHD1 expression." (PMID 41392286, 2025). "Thus, our strategy of selectively depleting of tumor-associated SAMHD1 presents a promising therapeutic approach, especially for cancers characterized by high SAMHD1 expression." (PMID 41392286, 2025). "As SAMHD1 mediates the poor response of cancer patients to chemotherapeutic treatment, depletion of SAMHD1 in tumor cells may offer a new anticancer strategy." (PMID 41392286, 2025). "Conversely, high SAMHD1 expression in Acute Myelogenous Leukaemia (AML) patients is associated with reduction in efficacy of the nucleoside-analogue anti-cancer drugs Cytarabine, Decitabine, Sapacitabine and Clofarabine29–33 as a result of SAMHD1 hydrolysis of their triphosphorylated forms." (PMID 38710701, 2024). "Indeed, we have shown that SAMHD1 depletion or degradation in cancer cells enhances sensitivity to Veliparib, a PARP inhibitor." (PMID 38406263, 2024). "USP7 inhibitors sensitize cancer cells to chemotherapy by decreasing SAMHD1." (PMID 38787520, 2024). "In cancer, SAMHD1 desensitizes cells to nucleoside-analogue chemotherapies." (PMID 38710701, 2024). "Furthermore, data from The Cancer Genome Atlas (TCGA) also indicate a positive correlation between USP7 and SAMHD1 expressions in various cancer types." (PMID 37081042, 2023). "Importantly, USP7 inhibitor sensitizes cancer cells to chemotherapy by decreasing SAMHD1, suggesting that SAMHD1 stabilization by USP7 promotes DNA damage repair to overcome oncogenic stress and affect chemotherapy sensitivity." (PMID 37081042, 2023). "The function of SAMHD1 in cancer is unclear; whether SAMHD1 plays the role of an oncogene or cancer suppressor remains controversial." (PMID 37009792, 2023). "Interestingly, ovarian and NSCLC cancer patients treated with antimetabolite plus platinum-based chemotherapeutic regimens presented lower ORR in case of SAMHD1 positivity (p = 0.04 and p = 0.016, respectively)." (PMID 35158911, 2022). "On the one hand, SAMHD1 plays tumor-suppressive roles in a variety of cancers." (PMID 35803902, 2022).
cancer (continued). "With the discovery of the ara-CTPase activity of the dNTP triphosphohydrolase SAM and HD domain-containing protein-1 (SAMHD1) resulting in limited ara-C activity in SAMHD1+ cancer cells as well as xenograft models, SAMHD1 was proposed as a novel target in AML patients." (PMID 35203388, 2022). "This will enable a better understanding of SAMHD1 as a target for cancer therapy." (PMID 34480199, 2022). "Human sterile α motif and HD domain-containing protein 1 (SAMHD1), originally described as the major cellular deoxyribonucleoside triphosphate triphosphohydrolase (dNTPase) balancing the intracellular deoxynucleotide (dNTP) pool, has come recently into focus of cancer research." (PMID 34480199, 2022). "This provides another likely dNTPase-independent mechanism of how SAMHD1 could be involved in cancer." (PMID 34480199, 2022). "However, SAMHD1 can hydrolyze several active triphosphate (TP) nucleoside analogs used for anti-cancer therapies." (PMID 35978833, 2022). "Alternatively, the role of SAMHD1 in cancer may relate to its functions in DNA repair and DNA replication, which are independent of dNTP degradation." (PMID 35158911, 2022). "Since then, our understanding of this enzyme has grown substantially, with additional biochemical activities and diverse biological roles reported, all of which paint a complex picture of the relationship of SAMHD1 with human health and disease, including cancer." (PMID 35583750, 2022). "Perhaps critically, these differential impacts of SAMHD1 upon cancer biology would be impacted by the cellular context, depending upon which oncogene is driving cancer cell proliferation, the metabolic wiring of the cell, and competency of genome stability pathways, for instance." (PMID 35583750, 2022). "Moreover, we developed novel in vitro models to explore the mechanisms driving SAMHD1 function in cancer development and treatment response." (PMID 35158911, 2022). "In this analysis, the association with mtDNA-CN levels was not attenuated (beta = 0.26; 95% CI, 0.19–0.32; p=7.8 × 10–15) suggesting that the effect of rare SAMHD1 variants on mtDNA-CN levels is not driven by its relationship with cancer status." (PMID 35023831, 2022). "Overall, our data provide strong evidence of the involvement of SAMHD1 function in advanced cancer." (PMID 35158911, 2022). "In summary, our data provide strong evidence of SAMHD1′s prognostic and predictive value in advanced cancers, which may be driven by SAMHD1′s role in DNA damage function." (PMID 35158911, 2022). "This indicates that mislocalization of SAMHD1 might not only contribute to pathogenicity in AGS but also in certain cancer types, namely CLL." (PMID 34480199, 2022). "As SAMHD1 is expressed to different levels in different tissues and cancers, the impact of SAMHD1 might vary depending on the tissue in question." (PMID 34480199, 2022). "SAMHD1 also inactivates the triphosphorylated forms of some anti-cancer nucleoside analogues." (PMID 34641952, 2021). "In addition, our TCGA analysis results and previous reports demonstrate downregulation of endogenous SAMHD1 expression in different cancer types." (PMID 33857133, 2021). "Similarly, among AML sublines adapted to a range of different anti-cancer drugs, only nucleoside analogues that displayed increased SAMHD1 and/ or decreased DCK levels were less sensitive to CNDAC." (PMID 34641952, 2021). "Notably, by analyzing the TCGA dataset, we demonstrated that SAMHD1 transcription is downregulated in many cancer types." (PMID 33857133, 2021). "We identified two SAMHD1 mutants (F59C and T232M), which could be involved in cancer development due to their inabilities to regulate normal TRC-dependent R-loop regulation." (PMID 33857133, 2021).
cancer (continued). "Therefore, SAMHD1-associated AGS provides an excellent experimental model for studying the comorbidity of AD and cancer." (PMID 33857133, 2021). "Our own results reveal a novel role of SAMHD1 for DNA DSB repair by NHEJ and give new insights into its implication in genome stability and cancer development, and corroborate a very recent report on a novel role of SAMHD1 in regulating class switch recombination in B lymphocytes." (PMID 33591315, 2021). "Unlike many other cancer-specific mutations, the SAMHD1 R366 mutations do not alter cellular protein levels of the enzyme." (PMID 34492268, 2021). "Importantly, this elevation of dNTP pools in cells expressing R366C/H SAMHD1 mimics the cancer cell phenotype." (PMID 34492268, 2021). "Importantly, as observed for SAMHD1 mutations in AGS cells, SAMHD1 cancer-associated mutations are found throughout the entire protein, and most cause reduced SAMHD1 protein levels." (PMID 34492268, 2021). "Finally, we sought to evaluate the contribution of SAMHD1 alterations in driving elevated dNTP levels, a key molecular signature of cancer, in a primary cell model." (PMID 34492268, 2021). "Therefore, modulation of SAMHD1 activity by drugs or potentially by Vpx targeting of SAMHD1 for proteasomal degradation has been proposed as a strategy for improving anti-cancer and anti-HIV therapies." (PMID 32576829, 2020). "In the iC3 subtype, which was associated with the most aggressive SKCM cases, FAM135B gene mutation frequencies were increased, while CD8A, GBP5, KIAA0040, and SAMHD1 expression were downregulated, suggesting that these genes play important roles in cancer development and immune responses." (PMID 32639949, 2020). "The SAMHD1‐dependent synergy for non‐allosteric RNRi was observed in multiple cancer cell lines and patient‐derived AML blasts and could be mechanistically linked to increasing intracellular ara‐CTP concentrations, leading to induced DNA damage and apoptosis." (PMID 31950591, 2020). "In conclusion, SAMHD1 protected cancer cell lines against dN-triggered toxicity." (PMID 32402273, 2020). "Furthermore, SAMHD1 catalytic activity modulates the efficacy of anti-cancer and anti-viral nucleoside analogues." (PMID 31296733, 2019). "Therefore, it is possible that this downregulation of SAMHD1 by HPV16 in keratinocytes persists throughout the transformation process through to HPV16-positive cancer cells." (PMID 31391281, 2019). "SAMHD1 has important anti-viral, anti-cancer and anti-inflammation functions in the cell." (PMID 31296733, 2019). "To determine whether SAMHD1 acetylation affects this phenomenon, we constructed stable cancer cell lines expressing wildtype SAMHD1 and K405R mutant." (PMID 28978134, 2017). "Alternatively, increasing SAMHD1 levels in cancer cells may slow cell growth by decreasing dNTP concentrations." (PMID 28046007, 2017). "As SAMHD1 controls the intracellular pool of dNTPs via its dNTPase activity, we hypothesized that SAMHD1 may also regulate cell proliferation in cancer." (PMID 28978134, 2017). "Here we highlight the importance of dNTP homeostasis in cancer and dNTP regulation by SAMHD1." (PMID 26416562, 2015). "Owing to its dNTPase activity, SAMHD1 may serve as an intriguing target of cancer therapy as reduction of dNTP pool may prevent tumorigenesis or an increase in efficacy of anti-nucleotide chemotherapeutics." (PMID 26416562, 2015). "By regulating dNTP homeostasis, SAMHD1 expression has implications in cancer." (PMID 26416562, 2015). "It is currently unclear whether SAMHD1 can degrade these nucleoside analogs in cells and reduce their anti-cancer potency." (PMID 26416562, 2015). "Therefore, it is conceivable that downregulation of SAMHD1 to reduce its dNTPase activity can contribute to cancer development because cancer cells can maintain a high dNTP pool to support their rapid DNA replication and cell proliferation." (PMID 24523981, 2013).